NLRP3 (NLR family pyrin domain containing 3)
Diseases named in the same sentence as NLRP3 in open-access papers (continued):
Sharing a sentence is not in itself a finding about the gene and the disease.
diabetes (continued). "Considering that alterations in DNA induced by oxidative stress contribute to diabetes progression, we addressed the in vitro and in vivo effects of mDNA released in response to pancreatic damage in T1D in the activation of NLRP3 inflammasome in macrophages." (PMID 28289409, 2017). "Since NLRP3 inflammasome regulates inflammatory pathways in diabetes, we examined serum amyloid A (SAA), a major prototypic marker of inflammation in rodents, as well as circulating levels of IL-1β and IL-18." (PMID 29435463, 2017). "Studies have shown that, in patients with type 2 diabetes mellitus, NLRP3 inflammasomes were up-regulated, and metformin treatment modulated the activation of these inflammasomes." (PMID 28708885, 2017). "More importantly, based on the beneficial effects of blocking the activation of the NLRP3 inflammasome, we provided a potential therapeutic target for clinical comorbidity and a new strategy for management of both diabetes and depression." (PMID 29084550, 2017). "Previous reports have indicated that the executor caspase of pyroptosis (activated caspase-1), which is induced by the NLRP3 inflammasome, is increased in a diabetic rat model and plays an important role in the development of diabetic cardiomyopathy." (PMID 29062465, 2017). "There is however a paucity of data on the gut microbiome in NLRP3−/− (NLRP3-KO) mice and its effect on diabetes-induced inflammation." (PMID 29435463, 2017). "The expression of the NLRP3 inflammasome subunits in adipose tissue correlates directly with body weight in mouse models and obese individuals with type 2 diabetes mellitus." (PMID 26980705, 2016). "These are the first data to implicate the NLRP3 inflammasome in diabetes remission after RYGB surgery." (PMID 26437377, 2015). "The increase of NLRP3 inflammasome at early stage of diabetes was accompanied with the decrease in cardiac function in diabetic rats, which indicated the importance of NLRP3 inflammasome in the pathogenesis of DCM." (PMID 25136835, 2014). "Chronic NLRP3 overactivity can lead to lung damage and fibrosis, cardiomyopathy, and consequences that may leave patients vulnerable to adverse effects of diabetes." (PMID 41522209, 2026). "While the cGAS-STING pathway's role in diabetic AF remains unclear, studies show that STING knockout or inhibition reduces diabetes-related cardiac inflammation by suppressing NLRP3 inflammasome activation." (PMID 41356195, 2026). "Vildagliptin was superior in alleviating diabetes-induced lung dysfunction by inhibiting NLRP3-mediated pyroptosis, oxidative stress, inflammation and could restore the histopathological architecture of the lungs." (PMID 40562805, 2025). "Conclusively, inhibition of PTP1B via Viscosol could attenuate meta-inflammation by suppressing the aberrant NLRP3 and AIM2 inflammasome signaling in diabetes-linked pathophysiology." (PMID 40173145, 2025). "Sepsis may increasingly be conceptualized as a syndrome of immunometabolic dysfunction, wherein inflammasome activation—particularly NLRP3—interacts with comorbid conditions such as diabetes." (PMID 40558557, 2025). "DAPA may improve liver glucose and lipid metabolism and function in diabetes model mice by inhibiting NLRP3-Caspase-1 signal transduction and regulating mitochondrial oxidative stress." (PMID 40136402, 2025). "Recent findings highlight the pivotal role of the NLRP3 inflammasome in diabetes progression." (PMID 40260393, 2025). "TXNIP activates NLRP3 inflammasome complex formation, triggers mitochondrial stress-induced apoptosis and inflammatory cell death, as a potential therapeutic target in various diseases, such as diabetes, chronic kidney disease, and neurodegenerative diseases." (PMID 39744566, 2025). "Additionally, a relatively recent report confirmed the increased levels of NLRP3 in the saliva or serum of patients with moderate periodontitis than healthy individuals or those with diabetes only." (PMID 41440367, 2025).
diabetes (continued). "NLRP3-driven production of IL-1β and IL-18 contributes to the tissue damage observed in various autoimmune and autoinflammatory diseases, such as gout, rheumatoid arthritis, type 2 diabetes mellitus, cardiovascular disorders, and infectious diseases." (PMID 40307577, 2025). "Studies identified that inhibiting the NLRP3 inflammasome activation could alleviate diabetes and diabetes complications." (PMID 41264598, 2025). "Moreover, metabolic imbalances in diabetes due to hyperglycemia can activate the NLRP3 oligomerization and the subsequent related events that cause cell injury and death." (PMID 40257540, 2025). "Additionally, interventions such as NLRP3 inflammasome inhibitors, antioxidants, and gut microbiota modulation are gaining attention for their potential in diabetes prevention and treatment." (PMID 40260393, 2025). "In the context of DN, inflammatory factors and the nucleotide - binding oligomerization domain - like receptor protein 3 (NLRP3) inflammasome emerge as pivotal players, exerting profound influences on both diabetes progression and the onset and advancement of renal fibrosis in DN." (PMID 41394140, 2025). "The increase in the levels of NLRP3 inflammasome components may indicate their involvement in the exaggerated periodontal inflammation as well as in the pathogenesis of diabetes." (PMID 41440367, 2025). "In this study, considering that NLRP3 inflammasome activation mediates chronic, unpredictable, mild stress-induced depression and depressive-like behaviors in diabetes patients, we evaluated the impact of repeated administration of MCC950 on PTX-associated anxiety- and depressive-like behaviors." (PMID 40002330, 2025). "Further detailed research could explore the specific mechanism of action of the main active ingredients of CE in against diabetes-induced cognitive dysfunction as well as the exact role of CE in the inhibition of NLRP3 inflammasome activation." (PMID 40257540, 2025). "Overall, our results demonstrated that Viscosol exhibits anti-inflammatory activity by reversing the NLRP3 and AIM2-mediated inflammation in diabetic neuro and nephropathy, thus making it a potent therapeutic drug for the treatment of diabetes-linked pathophysiology." (PMID 40173145, 2025). "Indeed, podocyte-specific suppression of the NLRP3 inflammasome prevents diabetes-induced proteinuria." (PMID 39920111, 2025). "Additionally, the presence of NLRP3/IL-1β/caspase-1 has been detected in individuals with conditions such as diabetes, myocardial infarction, arrhythmia, and cardiac hypertrophy." (PMID 38248345, 2024). "The study analyzed the expression of lncRNA MALAT1 and NLRP3 in lower limb atherosclerotic disease in diabetes patients, explored the relationship between them and the disease, and whether lncRNA MALAT1 may be a new biomarker of LEAD." (PMID 38439031, 2024). "Accumulating evidence shows the relationship between diabetes and NLRP3 inflammasome." (PMID 38637900, 2024). "One of the important signals during NLRP3 initiation and activation is diabetes-induced hyperglycemia and hyperlipidemia, which can promote ROS overexpression to activate the NF-κB signaling pathway and thus the transcription of NLRP3, pro-IL-1β, and pro-IL-18." (PMID 39021834, 2024). "Furthermore, melatonin suppressed neuronal pyroptosis and enhanced autophagy induced by diabetes through reducing the levels of Beclin1, NLRP3, ATG12, caspase-1, GSDMD-N, and LC3 in vivo and in vitro." (PMID 37697221, 2024). "The P2X7R/NLRP3/IL‐1β pathway is an important pathological mechanism of diabetes and depression." (PMID 38752512, 2024). "Accordingly, we hypothesized that NLRP3 dysregulation might affect pyroptosis in diabetic ED and evaluated pyroptosis markers (GSDMD, GSDMD-N, pro-caspase-1, cleaved-caspase-1, ASC, IL-1β, and IL-18)." (PMID 39014129, 2024).
diabetes (continued). "This suggests that the P2X7R/NLRP3/caspase-1 implicated pyroptosis and inflammatory scenario may serve as a potential target for the management of comorbid DNP and MDD in diabetes." (PMID 38256257, 2024). "It is found that the expression of NLRP3 inflammasome in diabetes patients with lower limb arterial disease is significantly increased, which may participate in the pathological progress of the disease." (PMID 38439031, 2024). "Liraglutide decreased expression of NLRP3, IL-18, and IL-1β pigs and mice with diabetes." (PMID 41424495, 2024). "Modifying factors, such as comorbid obesity, diabetes, or cardiovascular disease, may contribute to continuous upregulation of NLRP3 following head trauma and contribute to the pathogenesis of chronic mTBI symptoms or impairments." (PMID 38702410, 2024). "Previous studies have demonstrated the impact of rosemary on the inflammasome pathway, with components such as carnosic acid (CA) and carnosol (CAR) modulating NLRP3 inflammasome components in various diseases, including rheumatoid arthritis, diabetes, cancer, and neurodegenerative diseases." (PMID 39165924, 2024). "Liraglutide decreased expression of NLRP3, IL-18, and IL-1β in mice and pigs with diabetes." (PMID 41424495, 2024). "Diabetes induces a chronic inflammatory state in the body, with increased levels of the nucleotide-binding oligomerization domain-like receptor family, pyrin domain-containing 3 (NLRP3) inflammasome." (PMID 38672121, 2024). "Interestingly, some studies indicate that the activation of AMPK can reduce the upregulation of NLRP3 inflammasome in some pathological processes including diabetes, pain, ischemic stroke and endoplasmic reticulum stress." (PMID 39545058, 2024). "IRE1α cleavage of miR17 leads to thioredoxin-interacting protein (TXNIP) accumulation, the activation of the NLRP3 inflammasome, and caspase-1-dependent interleukin (IL)-1β production, which can trigger pyroptosis that contributes to diabetes progression in humans and mice." (PMID 38744890, 2024). "Moreover, in diabetes mellitus rats that received orthodontic treatment, NLRP3 was involved in diabetes-induced periodontal changes." (PMID 39769377, 2024). "Moreover, those covariates such as comorbidities (e.g., alcohol-related disease, hypertension, diabetes, depression, tobacco use) were proxies to the NLRP3 expression for the incident cancer." (PMID 38649928, 2024). "Sustained activation of the NLRP3 inflammasome resulted in delayed corneal wound healing and impaired nerve regeneration in WT mice with diabetes, whereas corneal epithelial wound closure and neurogenesis were significantly accelerated in NLRP3−/− mice with diabetes." (PMID 38957662, 2024). "The results above suggested that a relationship between the two forms of cell death via NLRP3 and suppress it could take on a protective effect against diabetes." (PMID 38987672, 2024). "NLR-family pyrin domain-containing protein 3 (NLRP3), as an important inflammasome, has a close connection with multiple chronic inflammatory diseases and metabolic disorders such as obesity, hypertension, diabetes, and so on." (PMID 37175227, 2023). "We found that coptisine repressed renal fibrosis induced by diabetes through suppressing the NLRP3 inflammasome, indicating that coptisine may become a promising drug for the treatment of diabetic nephropathy." (PMID 37197172, 2023). "Therefore, in this review, we explore the potential relationship between NLRP3 inflammatory vesicles in diabetes and COVID-19." (PMID 37868953, 2023). "CY-09 significantly ameliorates metabolic disorders in a diabetic mouse model, and can also alleviate inflammation, oxidative stress, and fibrosis in diabetic mice by selectively inhibiting NLRP3 inflammasome, thereby improving renal damage in diabetic nephropathy." (PMID 38250736, 2023).
diabetes (continued). "Diabetic retinopathy (DR), a microvascular complication of diabetes, is associated with pronounced inflammation arising from the activation of a nucleotide-binding and oligomerization domain-like receptor (NLR) protein 3 (NLRP3) inflammasome." (PMID 36835288, 2023). "Diabetes-induced lung dysfunction was effectively ameliorated with the use of quercetin via inactivating NLRP3-mediated pyroptosis, which may be a new strategy to mitigate diabetic complications." (PMID 36648717, 2023). "The specific regulatory mechanisms of NLRP3 inflammasome activation remain unclear, and lncRNAs were shown to modulate NLRP3 activation in diabetes." (PMID 38053839, 2023). "Thus, determining the role of NLRP3-activating related ion channels in the development of diabetes is important for improving insulin resistance." (PMID 36378463, 2023). "However, diabetes-induced podocyte loss and glomerular lipid accumulation were suppressed in STZ-injected NLRP3 knockout mice or NLRP3 inflammasome-specific inhibitor-administered db/db mice." (PMID 37373116, 2023). "Diabetes, obesity, atherosclerosis, and stroke are triggers that can activate endothelial cells to increase NLRP3 expression, which may contribute to endothelial dysfunction." (PMID 37564649, 2023). "AGE-RAGE pathway is believed to be related to the activation of NLRP3 inflammasome in diabetes." (PMID 37697234, 2023). "Furthermore, LPS-Exos have also been found to affect the NF-κB or NLRP3 signaling pathway, regulate macrophage polarization, reduce inflammation and facilitate tissue repair in kidney injury, diabetes, nerve injury, and myocardial infarction disease models." (PMID 37716974, 2023). "Accumulating evidence indicates that NLRP3 is involved in diabetes mellitus kidney damage." (PMID 37261217, 2023). "Abnormal activation of the NLRP3 inflammasome is closely related to the occurrence and development of different diseases in various systems, such as Alzheimer's disease, coronary atherosclerosis and diabetes." (PMID 36378463, 2023). "In addition, research suggests that inhibiting SGLT-2 modifies the expression and activity of the NLRP3 inflammasome, which in turn has a favorable effect on renal function in mice with type 2 diabetes mellitus." (PMID 37566054, 2023). "To investigate the potential anti-inflammatory role of ELA in GECs, we first examined whether NLRP3 inflammasome formation and activation were involved in diabetes-induced GECs in vivo." (PMID 37540330, 2023). "NLRP3 inflammasome-mediated neuronal pyroptosis and neuroinflammation have been demonstrated to be involved in the development of various neurological diseases, including AD, cerebral ischaemia-reperfusion injury and diabetes-induced brain injury." (PMID 37932279, 2023). "Only NLRP3 had a significant contribution to the likelihood of depression analyzed with age, body mass index, diabetes comorbidity, use of additional medication, Gensini score, duration between myocardial infarction, and blood collection as covariates (p = 0.015, OR = 1.72, and CI = 1.11-2.66)." (PMID 37763063, 2023). "Inflammasome activation of the nucleotide-binding domain, leucine-rich–containing family, and pyrin domain–containing-3 (NLRP3) has been observed to be involved in the pathogenesis of numerous inflammatory diseases, including prediabetes (PD) and type 2 diabetes mellitus (T2DM)." (PMID 37238986, 2023). "The NLRP3 inflammasome contributes to many metabolic diseases such as diabetes and obesity." (PMID 38069047, 2023). "This supports that WAT NLRP3 inflammasome/IL-1β pathway is a mechanism linking hyperapoB to diabetes risk, however; it does not exclude other mechanisms." (PMID 37914804, 2023). "Moreover, the combined of Yijinjing and resistance training has proven effective in inhibiting the robust NLRP3 inflammasome activation, thereby alleviating insulin resistance and liver injury in elderly pre-diabetes." (PMID 37859981, 2023).
diabetes (continued). "Moreover, we also observed that the expression levels of NLRP3 and cleaved IL-1β were up-regulated in heart tissues of CD38flox mice with diabetes, but their expression levels were reduced in the CD38-deficient group compared with control mice under diabetes." (PMID 37958991, 2023). "Under physiological conditions, NLRP3 inflammatory vesicles are necessary for corneal injury repair and nerve regeneration, however, in the case of diabetes, continued activation of NLRP3 inflammatory vesicles leads to delayed corneal wound healing and impaired nerve regeneration." (PMID 37443131, 2023). "In a rat model of diabetes, low levels of miR-23a in the liver targeted NIMA-related kinase 7 (NEK7), leading to its upregulation to activate pyroptosis caused by NLR Family Pyrin Domain Containing 3 (NLRP3) activation." (PMID 37371692, 2023). "To sum up, we speculated that the combined Yijinjing and resistance training may be an effective strategy to inhibit the robust NLRP3 inflammasome activation, thereby alleviating liver injury and insulin resistance in pre-diabetes." (PMID 36817440, 2023). "Furthermore, considering diabetes as a metabolic syndrome, the accompanying pro-inflammatory effects facilitate more production of inflammasome NLRP3, therefore adding to the pyroptosis of tissue cells in the lungs of COVID-19 patients." (PMID 37964954, 2023). "The NLRP3 inflammasome’s role in diabetes remains a topic of profound interest for research." (PMID 37762961, 2023). "Finally, we assessed the effects of LncRNA AC040162.3, miR-223-3p, and NLRP3 on the progression of HCV-induced diabetes." (PMID 37359091, 2023). "Surprisingly, very few studies have directly investigated the presence or the effect of inflammation, much less NLRP3-driven inflammation, on detrusor function during diabetes, although some studies have identified classic pro-inflammatory cytokines and signaling pathways being active." (PMID 36505062, 2022). "Whether there are other mechanisms of H2S inhibiting the NLRP3 inflammasome in diabetes requires further study." (PMID 35563208, 2022). "The expression of NLRP3/IL-1β/caspase-1 has been observed in patients with diabetes, myocardial infarction, arrhythmia, and cardiac hypertrophy, and some agents can improve the symptoms of cardiovascular disease in patients by inhibiting the occurrence of pyroptosis." (PMID 35647057, 2022). "A growing body of evidence supported NLRP3-inflammasome-mediated inflammation as one of the most important contributors to the pathogenesis of DM and its complications, including diabetes, diabetic nephropathy, diabetic retinopathy, and diabetic cardiomyopathy 6,16,18." (PMID 35002527, 2022). "The NLRP3 inflammasome and its products IL-1β and IL-18 may be potential targets for diabetes therapy." (PMID 36012516, 2022). "Recent studies suggest that NLRP3 inflammasome may be a potential new target for the treatment of diabetes mellitus." (PMID 36157218, 2022). "Chronic inflammation is an important pathophysiological factor leading to diabetes, which is manifested by higher levels of Nod-like receptor protein 3 (NLRP3), Caspase-1, Interleukin-1β (IL-1β), and various antiviral inflammatory cytokines, inducing a strong inflammatory response in the body." (PMID 36248820, 2022). "Thus, there is considerable evidence that NLRP3-induced inflammation is having significant detrimental effects on the detrusor during diabetes which clearly warrants more in-depth studies." (PMID 36505062, 2022). "In other studies, it was shown that MCC950 could effectively alleviate diabetes-induced renal damage by inhibiting the NLRP3/Caspase-1 pathway, which may be a potential therapeutic strategy for preventing the progression of diabetic nephropathy." (PMID 35566282, 2022).